IL6R (interleukin 6 receptor)
Diseases named in the same sentence as IL6R in open-access papers (continued):
Sharing a sentence is not in itself a finding about the gene and the disease.
prostate carcinoma (26 papers, 2003 to 2025). A carcinoma that arises from epithelial cells of the prostate gland. "An increase in risk of high-grade prostate cancer was found in carriers of the IL6R Asp358Ala variant (aOR = 1.3, 95%CI: 1.0–1.7)." (PMID 22792137, 2012). "IL6R has also been implicated in other cancer types, including prostate cancer." (PMID 35336739, 2022). "The IL-6/IL-6R signaling pathway could be considered a molecular marker associated with the progression of prostate cancer." (PMID 35464825, 2022). "Other receptors, IGFR and IL-6R have also been implicated in prostate cancer." (PMID 20126616, 2010). "The expression of IL-6 and IL-6R in prostate cancer, as well as the role of IL-6 as a growth factor in prostate cancer, was well documented." (PMID 35464825, 2022). "This highlights the feasibility of generating a therapy directed against the IL6R/STAT-3 axis in advanced stages of prostate cancer with these characteristics." (PMID 35465350, 2022). "pStat3 and IL6R levels were explored in metastatic tissues, showing the bone metastatic lesions of prostate cancer express high levels of pStat3 and IL6R." (PMID 31366128, 2019). "Exogenous IL-6 leads to the production and secretion of IL-6 and PEc from prostate cancer cells and tumors, by activating IL-6R and JAK2/STAT3 pathway." (PMID 30134795, 2018). "It was determined that the media obtained from the co-culturing experiments was able to generate the IL-6 production in prostate cancer cells and this effect was abolished when the anti-IL-6R antibody was introduced into the media." (PMID 30134795, 2018). "Mir-23a and miR-23b are downregulated in prostate cancer cells and have been shown to target IL6R, and as such have been proposed as therapeutic targets for prostate cancer." (PMID 30603058, 2018). "Several phase I/II clinical trials are currently evaluating antibodies against IL-6 or IL-6R as therapeutic alternatives for prostate cancer and renal cancer." (PMID 26989335, 2016). "The prostate cancer cell line LNCaP, used as an IL6R positive control, had similar expression levels of IL6R and IL6ST compared to ES cell lines." (PMID 26215971, 2015). "Prostate tumor cells produce large amounts of IL-6 and its receptor, IL-6R (gp80), and IL-6 functions as a paracrine growth factor for the human LNCaP androgen-sensitive prostate cancer cells and an autocrine growth factor for the human DU145 and PC3 androgen-insensitive prostate cancer cells." (PMID 36034203, 2022). "Interestingly, we observed that the DU145 cells exhibited a higher expression of the IL6R and a constitutive expression of pSTAT-3 when compared with the 22Rv1 and LNCaP prostate cancer cells." (PMID 35465350, 2022). "Finally, the disruption of the IL6R/STAT-3 axis in prostate cancer cells and the blocking of TIGIT on NK-92 were observed to increase the cytotoxicity of NK-92 cells against DU145 cells through an increase in sFasL, granzyme A, granzyme B, and granulysin." (PMID 35465350, 2022). "Prior to determine if this effect is associated with the JAK2/STAT3, protein extracts from prostate cancer cells under the influence of IL-6 with and without the treatment of anti-IL-6R antibody were examined for the phosphorylation of JAK2 and STAT3." (PMID 30134795, 2018). "The predominant activation of trans-signaling IL6/soluble IL6R pathway in aggressive prostate cancer, together with the functional IL6R Asp358Ala influence in this mechanism, supports the increased risk for high-grade prostate cancer we observed for C carriers (Ala carriers)." (PMID 22792137, 2012). "Furthermore, IL6R Asp358Ala and IGF1R +3174 SNPs were significantly associated with early-onset prostate cancer, possibly due to accelerated tumor formation." (PMID 22792137, 2012).
prostate carcinoma (continued). "The development of IL-6R superantagonists should allow the role of IL-6 in hormone-dependent and -independent conditions, such as breast and prostate cancer, to be elucidated and may lead to their use as novel therapeutic options for their treatment." (PMID 12592380, 2003). "In addition, IL-6/IL-6R is known to be the key signaling pathway in prostate cancer." (PMID 29868029, 2018). "Our results reveal that the combined use of inhibitors directed against the IL6R/STAT-3 axis and TIGIT enhances the functional activity of NK cells against castration-resistant prostate cancer cells." (PMID 35465350, 2022). "We first assessed the basal expression of the IL6R, STAT-3, and pSTAT-3 in 22Rv1, LNCaP, and DU145 prostate cancer cells." (PMID 35465350, 2022). "The combined inhibition of IL6R and HMGB1 has been reported to be a new treatment for enzalutamide resistance in patients with advanced prostate cancer." (PMID 34858477, 2021). "A knockdown of STAP-2 may inhibit prostate cancer cell growth by synergistically inhibiting EGFR and IL6R signaling." (PMID 36010693, 2022). "However, no studies have currently reported using a strategy to combat prostate cancer using both blockade of TIGIT and the disruption of the IL6R/STAT-3 axis." (PMID 35465350, 2022). "IL-6Rα was detected at low levels in MDA-MB231 and PC3 cells (<2%) relative to the unstained controls, whereas its expression in C4-2B prostate-cancer cells reached ~93% relative to its unstained control." (PMID 35200430, 2022). "Therefore, this study determines if the combined blockade of IL6R/STAT-3 and TIGIT enhances NK cell cytotoxicity against prostate cancer cells." (PMID 35465350, 2022). "The IL-6Rα (and Signal transducers and activators of transcription 3 (STAT3) oncogenic pathway) expression in aggressive, castration-resistant prostate cancer has recently been assessed in patients, making this receptor and pathway of high interest for targeting therapeutic interventions." (PMID 32046108, 2020). "Due to the fact that mouse IL-6, secreted by mouse macrophages and natural killer cells, is not able to activate the human IL-6R we examined the IL-6 expression in human prostate cancer cells after co-incubation with mouse IIR cells." (PMID 30134795, 2018). "Prostate cancer cell lines under the influence of the IR (innate or adaptive) presented a significant increase of IGF-1Ec upregulation (similar to the one observed after IL-6 treatment) (p < 0.001, students t test, n = 3) which was abolished when these cells were treated with anti-IL-6R antibody." (PMID 30134795, 2018).
Castleman disease (25 papers, 2013 to 2025). Castleman disease (CD) is a benign lymphoproliferative disorder that may present as a localized or multicentric form. "Therapeutic targeting of IL-6 in chronic inflammatory diseases mainly relies on the two IL-6R antibodies tocilizumab and sarilumab, while the siltuximab directed against IL-6 has been approved for Castleman’s disease." (PMID 37838173, 2023). "We hypothesized that interleukin-6/interleukin-6 receptor/gp130 polymorphisms contribute to increased interleukin-6 and/or other components of the interleukin-6 signaling pathway in HIV-negative Castleman Disease patients." (PMID 23372742, 2013). "Tocilizumab, a humanized anti–IL-6R mAb that blocks both soluble IL-6R and membrane-bound IL-6R, has been approved by the FDA for the treatment of RA and shown to be an effective therapy for other inflammatory diseases, including Castleman's disease." (PMID 26840088, 2016).
colitis (25 papers, 2010 to 2025). Inflammation of the colon. "Although consistent to our previous data, similar macrophage numbers were observed in control and IL-6Rα-deficient colons, IL-6Rα deficiency largely attenuated lymphocyte recruitment in colitis." (PMID 29695802, 2018). "In the present study, we analyzed IL-6 mAb-treated and Il-6r-deficient mice in a model of DSS-induced colitis." (PMID 24993179, 2014). "In the present study, we compared Il-6r-deficient mice with mice treated with neutralizing IL-6 monoclonal antibody (mAb) in a model of dextran sodium sulfate (DSS)-induced colitis." (PMID 24993179, 2014). "Interestingly, a recent study reported that RNF128 deficiency in intestinal epithelial cells promoted colitis and colorectal tumorigenesis by interacting with IL-6Rα and glycoprotein gp130." (PMID 39809743, 2025). "Collectively, these experiments suggest that CCL-20 is expressed by M2-type macrophages in colitis and that the inability of IL-6Rα-deficient macrophages to polarise towards M2-type impedes on CCL-20 expression and presumably on recruitment of CCR-6-expressing cells." (PMID 29695802, 2018). "Notably, these data are in line with our previous observation of reduced lymphocyte counts in IL-6Rα-deficient mice in colitis." (PMID 29695802, 2018). "MiR-320, a tumor suppressor, targets IL-6R in CRC cells, inhibiting the IL-6R/STAT3 pathway and preventing colitis-associated CRC in mice models." (PMID 38185635, 2024). "MARCH3 negatively regulates IL-6/STAT3 signaling to limit colitis by targeting IL-6Rα ubiquitination of IL-6Rα at K401 and subsequent degradation." (PMID 39162488, 2024). "Mortality during the course of colitis with IL-6R blockade was substantially decreased in both WT and PTENΔDC mice." (PMID 35514976, 2022). "A significant up-regulation of genes encoding the following cytokines and their receptors—Il13, Il16, Il27, Il2rb, Il2rg, Il6r Il10ra, Faslg, Ltb, Osm, Spp1, Tnf, Tnfsf14—was noted in animals with colitis (CβG−)." (PMID 31590413, 2019). "Effector T cell-induced colitis in Rag1−/− mice, which was poorly rescued by Xiap−/− tTreg cells, was prevented by co-administration of anti-IL-6R." (PMID 29386580, 2018). "We aimed at addressing the function of γδ T cells and their chemoattraction via CCL-20 in our CAC model by injecting anti-γδTCR at day 3 of the 1.5% AOM/DSS protocol prior to the colitis phase of CAC into control and IL-6Rα-deficient animals." (PMID 29695802, 2018). "After proving the successful recombination for the Il-6r allele, we created a mouse model of acute DSS-induced colitis using female Il-6rfl/fl and Il-6r−/− mice." (PMID 24993179, 2014). "Our data suggest that IL-6 and IL-6R have an additional role in colitis, apart from the IL-6/IL-6R classic and trans-signaling." (PMID 24993179, 2014). "As previously demonstrated, in an acquired immunity-dependent T cell transfer colitis mouse model, IL-6 receptor (IL-6R) monoclonal antibodies (mAbs) prevented the development of colitis." (PMID 24993179, 2014). "In agreement with a previous report using Il-6r-deficient mice, our results demonstrated that neutralizing IL-6 mAbs slightly improved DSS-induced colitis." (PMID 24993179, 2014). "In conclusion, DBK successfully reduced inflammation in DSS-induced UC mice by modulating the IL-6/IL-6R and IL-17A/IL-17RA pathways, as evidenced by alleviated colitis symptoms, decreased pro-inflammatory cytokines (TNF-α, IL-6, IL-1β), and histological improvements." (PMID 40005956, 2025). "Since we found increased expression of costimulatory molecules and IL-6 levels in colitic PTENΔDC mice, we asked whether ablation of the microbiota or of IL-6R signaling rescues the high mortality observed in PTENΔDC mice during colitis." (PMID 35514976, 2022). "We found that miR-124 agomir could significantly decrease while LNA could significantly increase the IL-6R level in colon tissues of DSS colitis mice." (PMID 32153570, 2020).
colitis (continued). "To quantify CCR-6+ lymphocyte recruitment in 1.5% AOM/DSS-induced colitis, we examined total cell numbers from non-colitic and colitic control as well as IL-6Rα-deficient colons by FACS." (PMID 29695802, 2018). "In order to examine whether Tregs also suppress effector functions in lean and obese IL-6Rα-deficient mice in our CAC model, anti-CD25 antibody was i.p. injected at day 3 of the 1.5% AOM/DSS protocol just prior to the colitis phase of CAC." (PMID 29695802, 2018). "Mice deficient in intestinal IL-6R (IL-6RΔIEC mice) did not display increased susceptibility to acute dextran sulfate sodium (DSS)-induced colitis." (PMID 27869785, 2016). "By employing in vitro methods of intestinal regeneration and in vivo mouse models of experimental colitis using a conditional deletion of the IL-6R in the intestinal epithelium (IL-6RΔIEC), we therefore investigated the influence of epithelial IL-6R on intestinal proliferation and repair." (PMID 27869785, 2016). "We further showed that although the IL-6R is the only known receptor for IL-6, the LysMCre+/−/Il-6rfl/fl and Il-6r−/− mice and their littermate controls had the same susceptibility to DSS-induced colitis." (PMID 24993179, 2014). "CNTF and p28 may play a beneficial role in DSS-induced colitis, as well as another unknown ligand for the IL-6R." (PMID 24993179, 2014). "IL-6Rα-deficient CD4+ CD45RBhi T cells failed to induce colitis when transferred into RAG2 KO mice and compared to WT mice, IL-6RαT-KO mice were also resistant to the induction of EAE following immunization with MOG35-55/CFA." (PMID 24842874, 2014). "This indicates that, under severe conditions of DSS-induced colitis, the knock out of Il-6r in neutrophils and monocytes may be beneficial to the survival of mice." (PMID 24993179, 2014). "With regard to this possibility, administration of IL-6R mAb to SCID mice, after transfer of CD45RBhigh T cells, confers protection from colitis, and IL-6–deficient mice have been shown to be less susceptible to colitis." (PMID 21966415, 2011). "Hence, the altered macrophage composition in IL-6Rα-deficient mice is not affecting the colitis phase of CAC but impacts on later stages of tumourigenesis." (PMID 29695802, 2018). "Thus, whereas colitis and colitis-associated proliferation is not affected by IL-6Rα deficiency, tumours of Il6rαKO mice exhibited less PCNA and Ki67 reactivity." (PMID 29695802, 2018). "Hence, the substantially reduced Ccl20 expression in colons of Il6rαKO mice is a consequence of collapsed M2-type polarisation of IL-6Rα-deficient macrophages in CAC, thereby compromising CCR-6-expressing lymphocyte recruitment in colitis to promote tumourigenesis." (PMID 29695802, 2018). "Moreover, even colitis-associated proliferation as examined via western blot analyses against the proliferation marker proliferating cell nuclear antigen (PCNA) was similarly detectable in control and IL-6Rα-deficient samples during colitis." (PMID 29695802, 2018). "We then analyzed the tissue-specific knockout of the Il-6r in mice with DSS-induced colitis, in order to exclude the possibility that the global knock out showed no phenotype, as the knock out in the myeloid cell lineage may compensate for the effects of the knock out in other cell types." (PMID 24993179, 2014). "Depletion of the gut microbiota using antibiotics as well as blocking IL-6R signaling rescued mortality in PTENΔDC mice, whereas adoptive transfer of Flt3L-derived PTEN-/- DCs into WT recipients exacerbated DSS-induced colitis and increased mortality." (PMID 35514976, 2022). "Notably, PTENΔDC mice treated with blocking IL-6R antibody showed similar mortality to DSS-induces colitis as WT mice without the blocking antibody." (PMID 35514976, 2022). "Our data revealed that the IL-6R does not play any role in DSS-induced colitis." (PMID 24993179, 2014).
colitis (continued). "At this point of understanding, it would be reasonable to breed double-deficient mice, which express neither IL-6 nor IL-6R (Il-6−/−/Il-6r−/−), and challenge them in comparison with Il-6−/−/Il-6r+/+, Il-6+/+/Il-6r−/− and Il-6+/+/Il-6r+/+ mice in a model of DSS-induced colitis." (PMID 24993179, 2014). "Alternatively, if the double-deficient mice are as susceptible to DSS-induced colitis as Il-6−/−/Il-6r+/+ mice, this would suggest that IL-6 has another unknown receptor, which mediates the detrimental IL-6 signal in colitis, while IL-6R plays no role." (PMID 24993179, 2014). "In addition, IL-6R signaling in T cells is a prerequisite for induction of T cell mediated colitis since its blockade has been shown to abrogate proliferation of CD4+ or CD8+ T cells, IFNγ production and induction of colitis in models of T cell transfer colitis." (PMID 35514976, 2022). "However, as the IL-23R is upregulated in Th17 cells in the T-cell-driven colitis model in the absence of Tec, it is tempting to speculate that Tec kinase regulates Th17 plasticity in an Th17-intrinsic mode by acting in the IL-6R signaling pathway." (PMID 35003062, 2021). "Il-6r-deficient mice and mice with tissue-specific deletion of the Il-6r in the myeloid cell lineage (LysMCre) with acute and chronic DSS-induced colitis were, however, indistinguishable from wild-type mice." (PMID 24993179, 2014). "Il-6r-deficient mice and mice with tissue-specific deletion of the Il-6r in the myeloid cell lineage (LysMCre) with acute and chronic DSS-induced colitis were, however, indistinguishable from wt mice." (PMID 24993179, 2014).
melanoma (25 papers, 2011 to 2025). A malignant, usually aggressive tumor composed of atypical, neoplastic melanocytes. "In melanoma, the tumor microenvironment induces the upregulation of Interleukin 6 Receptor (IL-6R) and Interleukin 10 Receptor (IL-10R) on DCs, activating the STAT3 signaling pathway and suppressing the Toll-like receptor (TLR)-driven maturation program." (PMID 41050070, 2025). "Along with our data, these collective observations reinforce the premise for ongoing phase 2 trials combining tocilizumab, an anti-IL-6R targeted antibody with ICIs in melanoma (NCT03999749) and NSCLC (NCT04691817)." (PMID 37852738, 2023). "The expression of β2‐AR was positively correlated with VEGF‐A and COX2 expression in melanoma metastasis and a trend for correlation between β2‐AR and IL6‐R expression was observed." (PMID 37551424, 2023). "Similar to the IL-6 level, the expression of the IL-6 receptor (IL-6R) also increases with melanoma progression, indicating an autocrine or paracrine function for IL-6 during melanoma progression." (PMID 27191257, 2016). "Critically, treatment with an IL-6R inhibitor (100 μg/dose, total 5 doses) significantly decreased liver metastases of ceramide-MeWo cells, which indicates that stromal ceramide promotes melanoma liver metastasis via IL-6." (PMID 40280124, 2025). "The simulations propose that IL-6 secreted by high-E2F1 melanoma cells is sufficient to trigger the activation of the IL-6/IL6R/STAT3 axis in CD4+ immune cells, which could also trigger secretion of other inflammatory factors." (PMID 39544930, 2024). "This case illustrates that co-administration of anti-PD-1 with anti-IL-6R in patients with advanced melanoma and Crohn’s disease can be well tolerated and may attenuate or delay autoimmune exacerbation without impacting a positive anti-tumor effects." (PMID 27595932, 2016). "There are ongoing clinical trials in the first-line advanced melanoma setting of combining nivolumab-relatlimab with ipilimumab which demonstrated encouraging efficacy data in preliminary reports along with improvement of safety with addition of IL-6R inhibitor." (PMID 41282765, 2025). "We explored the expression of beta‐2 adrenergic receptor (β2‐AR), interleukin 6‐receptor (IL6‐R), cyclooxygenase 2 (COX2) and VEGF‐A by immunohistochemistry in melanoma to assess the correlation between these proteins in melanoma cells and response to treatment." (PMID 37551424, 2023). "To evaluate whether this enhanced IL-6 signaling mediated JAK1/2 activation, we blocked IL-6 and IL-6R with anti-IL-6 and anti-IL-6R antibodies, respectively, at concentrations that were sufficient to inhibit IL-6-induced p-STAT3 in melanoma cells." (PMID 36008408, 2022).